GFOD1 (Gfo/Idh/MocA-like oxidoreductase domain containing 1)
Description:
Probably catalytically inactive enzyme. Does not bind NAD or NADP.
Synonyms: C6orf114; FLJ20330; ADG-90
Tractability: Antibody: UniProt places it where antibodies can reach, with high confidence; UniProt predicts a signal peptide or a membrane-spanning region; its Gene Ontology location is reachable by antibodies, with medium confidence; the Human Protein Atlas places it where antibodies can reach. PROTAC: ubiquitination databases record sites on it; its protein half-life has been measured.
Gene: Protein-coding gene on chromosome 6 (13,357,830 to 13,487,662, reverse strand). Ensembl gene ENSG00000145990.
Subcellular location: Secreted
Subcellular location (Human Protein Atlas): Cytosol; Nucleoplasm; Plasma membrane; Predicted to be secreted
Pathways (Reactome):
Signal Transduction: RHOQ GTPase cycle
Gene Ontology:
Molecular function: identical protein binding; protein binding; nucleotide binding
Cellular component: extracellular region
Genetic constraint (gnomAD): Loss-of-function variants: 9 observed, 24.94 expected, observed/expected ratio (o/e) 0.36, 90% interval 0.22 to 0.63. The upper end of that interval is the gene's LOEUF score, 0.63, which puts it in group 2 of 6, group 1 being the genes least tolerant of losing a copy. Missense variants: 403 observed, 569.17 expected, observed/expected ratio (o/e) 0.71, 90% interval 0.65 to 0.77. Synonymous variants: 253 observed, 256.4 expected, observed/expected ratio (o/e) 0.99, 90% interval 0.89 to 1.1.
Homologues: Orthologues: chimpanzee GFOD1 (100% identical), macaque GFOD1 (100% identical), mouse Gfod1 (98% identical), pig GFOD1 (98% identical), rat Gfod1 (98% identical), guinea pig GFOD1 (97% identical), dog GFOD1 (97% identical), rabbit GFOD1 (96% identical), tropical clawed frog gfod1 (93% identical), zebrafish gfod1 (85% identical), Drosophila melanogaster CG17712 (43% identical). Paralogues in human: GFOD2 (62% identical), DHDH (16% identical), BLVRA (11% identical).
Diseases named in the same sentence as GFOD1 in open-access papers:
GFOD1 is named in the same sentence as 11 diseases in open-access papers, as found by Europe PMC text mining. Sharing a sentence is not in itself a finding about the gene and the disease. The quoted sentences say what the papers report.
attention deficit-hyperactivity disorder (2 papers, 2010 to 2022). A disorder characterized by a marked pattern of inattention and/or hyperactivity-impulsivity that is inconsistent with developmental level and clearly interferes with functioning in at least two settings (e.g. at home and at school). "Increased expression of GFOD1 has been noted in the hippocampal tissue of patients with temporal-lobe epilepsy and patients with attention deficit hyperactivity disorder." (PMID 36468003, 2022). "GFOD1, another expression correlate of SBP and DBP is a gene of unknown function which has been associated with attention deficit hyperactivity disorder." (PMID 20502693, 2010).
clear cell renal cell carcinoma (2 papers, 2016 to 2018). "However, GFOD1 is significantly upregulated in clear cell renal cell carcinoma tissues, but gradually decreased during cancer progression." (PMID 29738475, 2018).
bipolar disorder (1 paper, 2013). A disorder of the brain that causes unusual shifts in mood, energy, activity levels and the ability to carry out day-to-day tasks. "These include GFOD1, which is associated with attention deficit hyperactivity disorder (ADHD), DLGAP1 which is associated with schizophrenia, DOCK9 associated with bipolar disorder, and SORCS1 which is associated with memory." (PMID 24151499, 2013).
Megalencephalic leukoencephalopathy (1 paper, 2019). "We also observed only three overlapping genes between differentially expressed genes in these three selected modules: FGFBP2, GFOD1, MLC1, which were functionally enriched for revascularization, glycometabolism, Megalencephalic leukoencephalopathy with subcortical cysts pathways." (PMID 30683112, 2019).
migraine (1 paper, 2020). "The CpG island near the PHACTR1 migraine risk locus is overlapping the promoter region of various splice variants of the GFOD1 gene and the non-coding GFOD1-AS1 gene." (PMID 32076896, 2020). "Analysis of the gene expression in the GTEx database indicates that GFOD1 is expressed predominantly in brain and vascular tissue, which are tissue types that have been connected with migraine." (PMID 32076896, 2020).
oral cancer (1 paper, 2021). "Moreover, four genes (SERPINB2, GFOD1, TGFA, MXD1) were downregulated in these samples suggesting an inhibitory role in oral cancer cell invasion and metastasis." (PMID 34116687, 2021).
sarcopenia (1 paper, 2020). Progressive decline in muscle mass due to aging which results in decreased functional capacity of muscles. "A new prediction model with high accuracy can be developed based on four identified molecular markers (SEPP1, SV2A, GOT1, and GFOD1) and used by clinicians to predict the risk of sarcopenia." (PMID 33221762, 2020). "LASSO regression model was used to select 4 key differentially expressed (SEPP1, GFOD1, GOT1, and SV2A) mRNAs (DEMs) predictors of sarcopenia risk and the lasso parameter (lambda.min) was 0.01038519." (PMID 33221762, 2020). "SEPP1 mRNAs were upregulated and GFOD1, GOT1, and SV2A mRNAs were downregulated in the sarcopenia group." (PMID 33221762, 2020). "A new model for predicting sarcopenia based on four molecular markers SEPP1, SV2A, GOT1, and GFOD1 was developed." (PMID 33221762, 2020). "Besides, this study is the first to predict the occurrence of sarcopenia based on four molecular markers (SEPP1, SV2A, GOT1, and GFOD1)." (PMID 33221762, 2020). "Combined with the nomogram prediction model results, SEPP1, GFOD1, GOT1, and SV2A may be key modulators of sarcopenia." (PMID 33221762, 2020). "SEPP1 and DLEU2 expression levels were higher in patients with sarcopenia than in patients without sarcopenia, while the expression levels of GFOD1, GOT1, SV2A, and miR-181a were significantly lower in patients with sarcopenia than in patients without sarcopenia." (PMID 33221762, 2020).
cancer (2 papers, 2016 to 2018). A tumor composed of atypical neoplastic, often pleomorphic cells that invade other tissues. "The bioinformatics analysis showed that peejar and GFOD1 expression were significantly elevated in ccRCC tissues, but gradually decreased during cancer progression." (PMID 27191742, 2016). "Despite some cancer cells might also expressing GFOD1 and peejar, we are expecting that those GFOD1-expressing tumor infiltrated immune cells, like NK cells, Eosinophil cells and Macrophage cells might contributed to the prognosis." (PMID 27191742, 2016).
tumor (1 paper, 2016). "We found two high correlated DEGs, peejar and GFOD1 were associated with high ccRCC tumor stage, high ccRCC tumor grade and poor prognosis." (PMID 27191742, 2016). "In conclusion, our study demonstrated for the first time that lncRNA peejar and mRNA GFOD1 expression was significantly increased in ccRCC and decreased during tumor progression." (PMID 27191742, 2016). "We further evaluated the gene expression of GFOD1 and peejar by qRT-PCR in an independent sample of 50 CCRCC tumor samples and 36 non-tumor kidney tissues." (PMID 27191742, 2016).
GFOD1 also shares sentences with these, for which no sentence is quoted: schizophrenia (1 paper); temporal lobe epilepsy (1).